CDKN1A (cyclin dependent kinase inhibitor 1A)
Diseases named in the same sentence as CDKN1A in open-access papers (continued):
Sharing a sentence is not in itself a finding about the gene and the disease.
osteosarcoma (31 papers, 2009 to 2024). A usually aggressive malignant bone-forming mesenchymal neoplasm, predominantly affecting adolescents and young adults. "have demonstrated that WIPI1 promotes osteosarcoma cell proliferation by inhibiting CDKN1A expression." (PMID 36185204, 2022). "Our results are consistent with experiments in osteosarcoma cell lines that have shown that drug treatment induces growth arrest and increases levels of CDKN1A, MDM2, and BCL2L1." (PMID 24835790, 2014). "According to a very recent report, CDKN1A was upregulated by EVI1 in the human osteosarcoma cell line U2OS." (PMID 23457546, 2013). "The CtBP1-p300-FOXO3a complex can specifically repress the expression of two downstream targets, Bax and Bim, but not other known CtBP1 targets such as CDH1 (epithelial Cadherin), PTEN (Phosphatase and Tensin Homolog), and CDKN1A (Cyclin-Dependent Kinase Inhibitor 1A) in human osteosarcoma cells." (PMID 31754335, 2019). "For osteosarcoma, CDKN1A upregulation could inhibit the proliferation and cell cycle of the cells." (PMID 35340229, 2022). "Mechanistically, TSC01682 significantly inhibits osteosarcoma cell proliferation and invasion by downregulating DCAF11 and DCAF13 and upregulating CDKN1A (cyclin-dependent kinase inhibitor 1A, also known as p21) and PTEN." (PMID 39062505, 2024). "In conclusion, this study suggested that the miRNAs including miR-22-3p, miR-154-5p, miR-34a-5p, miR-485-3p, miR-93-5p, and miR-9-5p and the genes including LEF1, RUNX2, CSF1R, CDKN1A, and FBN1 act as key factors in the progression of osteosarcoma." (PMID 35340229, 2022). "CDKN1A was reported to interact with multiple HDACs, including HDAC4, in a human osteosarcoma cell line." (PMID 35242053, 2022). "In summary, this study suggests the miRNAs including miR-22-3p, miR-154-5p, miR-34a-5p, miR-485-3p, miR-93-5p, and miR-9-5p and the genes including LEF1, RUNX2, CSF1R, CDKN1A, and FBN1 are the key factors in the progression of osteosarcoma." (PMID 35340229, 2022). "In human osteosarcoma cells, after 24 h stimulation with 1,25(OH)D 100 nM we observed a significant upregulation of OCN, CDKN1A, CaBP9K and CYP24A1, which was blunted upon co-incubation with PFOA, with the exception of CaBP-9 K." (PMID 33033332, 2020). "Thus, this study suggests that the hub nodes LEF1, RUNX2, CSF1R, VAV3, FZD3, CDKN1A, and FBN1 are key factors in the progression of osteosarcoma." (PMID 35340229, 2022). "In human osteosarcoma cells, the induction of SHOX expression elevates CDKN1A and CDKN1B levels." (PMID 34122528, 2021). "Although Antxr1 knockdown was reported to reduce Ccnd1 and to increase Cdkn1a and Cdkn1b expression in osteosarcoma cells, their expression was not changed in the limb cartilage of Antxr1 tg mice compared with that in wild-type mice at E15.5 by microarray analysis (data not shown)." (PMID 32244499, 2020).
osteosarcoma (continued). "In contrast, induction of these target genes was significantly lower in all osteosarcoma cell lines, in particular BAX and CDKN1A, where no induction was observed for all time points and XI-006 concentrations." (PMID 26095524, 2015).
leukemia (26 papers, 2012 to 2026). A malignant (clonal) hematologic disorder, involving hematopoietic stem cells and characterized by the presence of primitive or atypical myeloid or lymphoid cells in the bone marrow and the blood. "From this approached also Zmat3 was implicated in development of lymphoma/leukaemia, but only when also Puma and Cdkn1a were depleted." (PMID 34362419, 2021). "In addition, CDKN1A/p21/WAF has been reported to be induced in response to several leukemia associated oncogenes and to play a role in protection from DNA damage in this context." (PMID 23457546, 2013). "Among the genes with significant changes upon TMIGD2 depletion were factors closely associated with cell-cycle (CDKN1A and CCND1) and leukemia stemness (CD93 and IL1RAP)." (PMID 38167704, 2024). "In mouse leukemias, Cdkn1a expression was decreased in pre-LSCs compared to wild-type DN3a thymocytes and was further reduced in leukemic cells, in both Cd3e+/+ and Cd3e-/- leukemias." (PMID 35401501, 2022). "The overexpression of these miRNAs reduces CDKN1A levels in leukemia cells, indicating that the anti-cancer activity of nitidine chloride is mediated by the c-Myc-miR-17–92 axis." (PMID 33066509, 2020). "Like what we observed in leukemia cell lines, the CDKN1A and PUMA gene expression significantly increased after DFX incubation." (PMID 33081324, 2020). "Indeed, we note that Cdkn1a is increased in both DKO leukemias and E2a-/-Lef1F/F leukemias after deletion of Lef1 compared to E2a-/- leukemias suggesting that Cdkn1a could be a TCF1 target that is repressed by LEF1." (PMID 35371057, 2022). "Validated targets concentrated on key leukemia-related genes like PTEN, BCL2L11, CDKN1A, CCND1, RB1, E2F1, and TGFBR2." (PMID 42123456, 2026). "A recent study demonstrated that nitidine chloride attenuates c-Myc expression levels via ubiquitin-mediated degradation and induces differentiation and apoptosis by upregulating cyclin-dependent kinase inhibitor 1A (CDKN1A, also known as p21Cip1) in leukemia." (PMID 33066509, 2020).
lung adenocarcinoma (26 papers, 2014 to 2025). A carcinoma that arises from the lung and is characterized by the presence of malignant glandular epithelial cells. "Besides, the analysis of The Cancer Genome Atlas (TCGA) lung adenocarcinoma dataset also indicated that CDKN1A expression was positively associated with immune score and cytotoxic cells enrichment." (PMID 38323313, 2024). "CDKN1A upregulation following radiotherapy promoted lung adenocarcinoma cell survival, as evidenced by the increased viability of irradiated CDKN1A-overexpressing lung adenocarcinoma cells." (PMID 38468925, 2024). "CDKN1A inhibits pyroptosis to enhance the radioresistance of lung adenocarcinoma cells by promoting DNA repair." (PMID 38468925, 2024). "Analysis of CDKN1A mRNA expression in 29 KRAS-mutant human lung adenocarcinoma cell lines revealed an inverse correlation with the previously published EMT gene signature." (PMID 34309585, 2021). "Radiotherapy upregulated CDKN1A expression, which promoted lung adenocarcinoma cell survival." (PMID 38468925, 2024). "The ceRNA mechanism, involving genes like TENM4, XRCC2, HDAC5, CDKN1A, ARFGEF3, SNAP25-AS1, RP11-58O9.2, LINC01164, VLDLR-AS1, and RP11-14I17.2, may play a role in lung adenocarcinoma (LUAD) development linked to tumor hypoxia." (PMID 39236027, 2024). "In the present study, CDKN1A enhanced radioresistance in lung adenocarcinoma cells." (PMID 38468925, 2024). "•CDKN1A confers radioresistance to A549 and H1650 human lung adenocarcinoma cells." (PMID 38468925, 2024). "Both confirmed that CDKN1A was the core of GMDS-mediated lung adenocarcinoma progression." (PMID 29843634, 2018). "Furthermore, IPA network analysis showed that CASP8-CDKN1A axis was at the core of GMDS-associated gene interaction network, emphasizing the core of CDKN1A in GMDS-mediated lung adenocarcinoma growth." (PMID 29843634, 2018). "Our findings indicate that CDKN1A inhibits the activation of AIM2 inflammasome by promoting DNA repair after radiotherapy, thus promoting the survival of lung adenocarcinoma cells." (PMID 38468925, 2024). "The CDKN1A and DAPK2 genes are notable for being negatively correlated with and targeted by multiple miRNAs from these clusters in the two most common subtypes of NSCLC (lung adenocarcinoma and SCC)." (PMID 36900258, 2023).
lymphoma (23 papers, 2010 to 2025). A malignant (clonal) proliferation of B- lymphocytes or T- lymphocytes which involves the lymph nodes, bone marrow and/or extranodal sites. "In agreement with the CDKN1A oncogenic activity, lymphomas arising in CDKN1A-deficient mice demonstrate a high rate of apoptosis." (PMID 34833004, 2021). "In further agreement with p21’s survival-enhancing activity, lymphomas arising in Cdkn1a-deficient mice demonstrate a high rate of apoptosis." (PMID 25838973, 2015). "Interestingly, later studies revealed that the Dino/Cdkn1a locus represents a tumor suppressor locus as loss of Dino can promote lymphoma in an Eμ-Myc mouse model as well as induce the formation of a subset of spontaneous tumors, including sarcomas and lymphomas." (PMID 37782337, 2024). "Previous work showed that BCL6 can form a transcriptional repressor complex with MIZ1 that represses CDKN1A expression in GC-derived lymphoma cell lines." (PMID 32407433, 2020). "Our current data indicate that this CDKN1A repression dependence of lymphoma cells is inherited from and based on the natural physiological function of EZH2 in GC B cells and is not an artifact of EZH2 somatic mutation or the malignant phenotype." (PMID 29026085, 2017). "Treatment of GC-derived lymphoma cell lines with EZH2 inhibitors was shown to induce CDKN1A mRNA expression." (PMID 29026085, 2017). "Interestingly, studies on tumor development in mice have demonstrated that the deletion of CDKN1A inhibits lymphoma." (PMID 34833004, 2021). "Finally, it is important to note that the mechanism by which EZH2 controls GC B cell proliferation through regulation of CDKN1A is also relevant to the malignant lymphomas that arise from GC B cells." (PMID 29026085, 2017). "A statin-induced cell cycle arrest and an accumulation of CDKN1A were shown in lymphoma cells." (PMID 25978957, 2015). "Interestingly, the absence of functional Miz1 led to attenuated tumorigenesis in mouse skin and in a murine lymphoma model, either by up regulation of Cdkn1a expression or by induction of senescence via an autocrine TGFβ signalling loop, respectively." (PMID 24586582, 2014). "MYCV394D is unable to repress wild-type MYC targets such as Cyclin Dependent Kinase Inhibitor 1A (CDKN1A/p21CIP) and Cyclin Dependent Kinase Inhibitor 2B (CDKN2B/p15INK4B), in a transgenic lymphoma model." (PMID 28505071, 2017). "CDKN1A, a pivotal regulator of the cell cycle, is directly repressed by BCL6 to enable unchecked cellular proliferation, thereby driving the rapid expansion of lymphoma cells." (PMID 39815148, 2025). "In lymphoma, the growth factor independent 1 (Gfi1) oncoprotein mediates the recruitment of the histone lysine methyltransferase G9a in complex with the histone deacetylase HDAC1 to the CDKN1A promoter." (PMID 31514410, 2019).
Obesity (21 papers, 2011 to 2026). Accumulation of substantial excess body fat. "Our work identified vascular dysfunction risk genes, including Sox17, Ulk4, Nbeal1, Cdkn1a and Plec, as obesity-regulated genes in the endothelium." (PMID 36400935, 2022). "It is noteworthy that induction of the p21/CDKN1A is associated with adipocyte hypertrophy and obesity in mice." (PMID 35425699, 2022). "Further genes upregulated in cardiac art ECs in obesity, including Hivep2 and Cfdp1, were associated with atherosclerosis, while CDKN1A, the gene encoding the senescence factor p21, was associated with heart failure." (PMID 36400935, 2022). "Due to its known susceptibility to epigenetic regulation and potential role in obesity, Cdkn1a has also recently been described as an epiobesigene." (PMID 21779332, 2011). "Notably, senescence-associated genes such as ID2, LMNA, CDKN1A, and CTNNB4 were dysregulated in obesity and partially reversed after surgery." (PMID 40847086, 2025). "A literature search uncovered one report suggesting that Cdkn1a, a cyclin-dependent kinase inhibitor, may have a role in the obesity-inducing effects of high-fat diet feeding beyond one generation." (PMID 25330228, 2014). "We found that MORC3, NUP62, CGAS, ABI3, and RPA2 were highly expressed in lean individuals, where as LMNA, ID2, CDKN1A, TENT4B, MME, and MYC were upregulated in the PBMCs of individuals with obesity." (PMID 40847086, 2025). "Transcriptomic analyses further revealed obesity-induced immune cell senescence through regulation of key genes (ID2, LMNA, CDKN1A), which could be reversed by bariatric surgery." (PMID 40847086, 2025). "Mature human adipocytes undergo senescence under obesity and hyperinsulinemia stimulation, exhibiting premature aging transcriptomic and secretory characteristics, including upregulation of CDKN2A, CDKN1A, and CCND1 gene expression, and downregulation of HMGB1 and HMGB2 gene expression." (PMID 39963130, 2025). "Adjusting for sex alone did not alter the significant upregulation of GLB1, ZMAT3, CDKN1A, and CDKN2A in individuals with obesity (Sup." (PMID 40127780, 2025).
neuroblastoma (17 papers, 2004 to 2024). Neuroblastoma (NB) is the most common solid, extracranial childhood tumor. "The increase in CDKN1A expression after treatment with retinoids was described in many human malignancies under in vivo and in vitro conditions: acute promyelocytic leukemia, acute T-lymphoblastic leukemia, pre-B lymphoma, hepatoblastoma, and neuroblastoma." (PMID 24959102, 2014). "In addition, the expression of several genes associated with growth suppression, including CDKN1A, EGR1, NRG1 and SEL1L, were also enhanced in all S(+)-ibuprofen-treated neuroblastoma cell lines." (PMID 24173829, 2014). "CDKN1A is induced by RA through RARB in human neuroblastoma tumors." (PMID 15345368, 2004). "The role of RNF11 in the TGFβ pathway is of particular interest in neuroblastoma given our previous finding that the miR-17∼92 cluster components target TGFBR2 and SMAD2 as well as TGFβ downstream regulated genes CDKN1A, ITGA4, and SERPINE1." (PMID 23308108, 2013).
non-small cell lung carcinoma (17 papers, 1999 to 2025). A group of at least three distinct histological types of lung cancer, including non-small cell squamous cell carcinoma, adenocarcinoma, and large cell carcinoma. "In non-small-cell lung carcinoma, treatment with HDACi alone or in combination with the natural flavonolignan silibinin caused increased H3 and H4 acetylation in the Sp1/Sp3 binding site at the CDKN1A promoter, activating CDKN1A transcription." (PMID 31514410, 2019). "Pharmacological senescence was induced in non-small cell lung cancer cells using doxorubicin, and the expression level of CDKN1A/p21 was measured at the single-cell level." (PMID 38139316, 2023). "CDKN1A mainly regulates the cell cycle and DNA damage repair, affecting the occurrence and development of non-small cell lung cancer." (PMID 35903358, 2022). "In addition, LncRNA AB073614 promotes tumor migration and invasion by repressing CDKN1A in non-small cell lung cancer." (PMID 39236027, 2024). "In non-small-cell lung cancer, the long noncoding RNA LINCO1133 recruits EZH2 and lysine-specific demethylase 1A (LSD1) to the CDKN1A promoter to repress its transcription, leading to a proliferative stimulus." (PMID 31514410, 2019). "In addition, in Non-small cell lung cancer, FZKA also act on PRKCA and CDKN1A (p21)." (PMID 30400936, 2018).